HMGB1 (high mobility group box 1)
Diseases named in the same sentence as HMGB1 in open-access papers (continued):
Sharing a sentence is not in itself a finding about the gene and the disease.
pulmonary hypertension (31 papers, 2014 to 2026). Increased pressure within the pulmonary circulation due to lung or heart disorder. "The inhibition of HMGB1 has been associated with decreased pulmonary vascular remodeling in different pulmonary hypertension rat models." (PMID 35204311, 2022). "Similarly, loss of prohibitin 1 in a rat model of pulmonary hypertension showed that the loss of prohibitin 1 resulted in increased high mobility group box 1 (HMGB1)-mediated vascular injury." (PMID 35407523, 2022). "Considering the pathophysiology of pulmonary hypertension and the role of HMGB1 in inflammatory processes and tissue remodeling, there is reasonable probability that HMGB1 may be associated with the pathogenesis of pulmonary hypertension, an angioproliferative vasculopathy." (PMID 25420924, 2014). "It has been proposed that pulmonary arterial endothelial cell ferroptosis mediates the progression of pulmonary hypertension through the MCT-induced HMGB1/TLR4/NLRP3 inflammasome signaling pathway in rats." (PMID 38111578, 2023). "For example, male SHR showed a higher serum mitochondrial DNA (TLR9 DAMP) when compared to females; likewise, in an animal model of pulmonary arterial hypertension, males showed a higher circulating HMGB1 (TLR4 DAMP) when compared to females." (PMID 35822020, 2021). "Elevated serum levels of HMGB1 in a rat model of pulmonary arterial hypertension were found to mainly result from alveolar macrophages and smooth muscle cells." (PMID 31523175, 2019). "Recently, high-mobility group box-1 (HMGB1), an inflammatory mediator, has received increasing attention for its role in the pathogenesis of pulmonary arterial hypertension." (PMID 31523175, 2019). "In this study, we investigated the relevance of HMGB1 in the pathological remodelling present in patients with idiopathic pulmonary arterial hypertension (IPAH) and pulmonary hypertension (PH) associated with COPD." (PMID 25726846, 2015). "Bioptic lung tissue revealed the presence of HMGB1-positive cells surrounding remodelled vessels both in COPD with pulmonary hypertension and in IPAH lung samples." (PMID 26798204, 2015). "Further studies are needed to confirm the potential of HMGB1 as a novel therapeutic target for pulmonary hypertension." (PMID 25420924, 2014). "The proportions of cytoplasmic-HMGB1-positive cells in lung tissue was higher in the MCT-induced pulmonary hypertension rats (65.4% ±6.5%) than in the normal control rats (6.7% ±0.8%; p <0.001)." (PMID 25420924, 2014). "We also demonstrated that inhibition of HMGB1 by GLY treatment improved the survival rates of MCT-induced pulmonary hypertension rats by reducing pulmonary hypertension and attenuating pulmonary vascular remodeling and RV hypertrophy." (PMID 25420924, 2014). "Treatment of pulmonary hypertension with GLY, an HMGB1 inhibitor, has the potential to attenuate pulmonary vascular remodeling and disease progression of pulmonary hypertension." (PMID 25420924, 2014). "High mobility group box-1 (HMGB1), a proinflammatory cytokine, plays a pivotal role in tissue remodeling and angiogenesis, both of which are crucial for the pathogenesis of pulmonary arterial hypertension." (PMID 25420924, 2014). "Likewise, NLRP3 inflammasome induction has been reported in a rat model of pulmonary hypertension after high mobility group box 1 (HMGB1) was released from ferroptotic cells, a critical DAMP that binds to TLR4." (PMID 39765769, 2024). "Indeed, experiments performed in transgenic mice overexpressing EC-specific hResistin supported the evidence of increased expression of EC-derived HMGB1 tempered hResistin-driven pulmonary vascular remodeling and pulmonary hypertension." (PMID 36984870, 2023). "In conclusion, we demonstrated that the proinflammatory cytokine HMGB1 could contribute to the pathophysiology of pulmonary hypertension." (PMID 25420924, 2014).
pulmonary hypertension (continued). "To examine the relationship between HMGB1 and pulmonary hypertension, we investigated the patterns and levels of HMGB1 expression in lung tissues at 28 days and measured serum levels of HMGB1 at 0, 1, 3, 7, 14, 21, and 28 days after inducing pulmonary hypertension by MCT." (PMID 25420924, 2014). "A recent study also reported that serum HMGB1 levels were higher in idiopathic pulmonary hypertension patients than in healthy controls, and HMGB1 may contribute to the pathogenesis of experimental pulmonary hypertension induced by chronic hypoxia." (PMID 25420924, 2014). "In this study, we explored the relationship between HMGB1 and pulmonary hypertension and whether glycyrrhizin, an inhibitor of HMGB1, attenuates disease progression in an animal model of pulmonary hypertension induced by monocrotaline sodium (MCT)." (PMID 25420924, 2014). "However, in lung tissues of the MCT-induced pulmonary hypertension rats, many inflammatory cells were recruited to the lungs, and HMGB1 was localized to both the nucleus and the cytoplasm." (PMID 25420924, 2014). "To determine whether HMGB1 plays a role in endothelial hyperactivity in pulmonary hypertension, we quantified ET-1 release from cultured HPAECs after stimulation with HMGB1." (PMID 25420924, 2014). "This study shared the same conclusion with that of our study: inflammatory cytokine HMGB1 likely plays a significant role in the pathophysiology of pulmonary hypertension; however, used animal model of pulmonary hypertension was different with that of our study." (PMID 25420924, 2014). "Therefore, the inhibition of HMGB1 by GLY treatment can attenuate hemodynamic changes in MCT-induced pulmonary hypertension rats." (PMID 25420924, 2014). "The response of smooth muscle cells to HMGB1 has been well-characterized in atherosclerotic plaques; however, migration and proliferation of vascular smooth muscle cells are also major pathological features in pulmonary-hypertension vascular lesions." (PMID 25420924, 2014). "Thus, the study by Bauer and co-workers was helpful in clarifying our results about the role of HMGB1 in pulmonary hypertension." (PMID 25420924, 2014). "A recent study from Bauer and co-workers reported that serum HMGB1 levels were higher in idiopathic pulmonary hypertension patients than in healthy controls, and HMGB1 may contribute to the pathogenesis of experimental pulmonary hypertension induced by chronic hypoxia." (PMID 25420924, 2014). "In other studies using MCT to establish a rat model of pulmonary hypertension (PH), peroxiredoxin 6 (PRDX6) was found to regulate ferroptosis in PAECs through HMGB1 release and activation of the TLR4/NLRP3 inflammasome signaling pathway." (PMID 38111578, 2023). "It has been reported that TMP has potent effects for the treatment of pulmonary hypertension by scavenging intracellular ROS.To clarify the effect of TMP in PASMCs, cells were incubated with TMP for 24 h in the presence of HMGB1." (PMID 37268944, 2023). "In this study, we found that HMGB1 levels in lung tissue and serum significantly increased in MCT-induced pulmonary hypertension rats." (PMID 25420924, 2014). "Cytoplasmic translocation of HMGB1 was also observed in vascular endothelial cells, smooth muscle cells, and recruited inflammatory cells in the MCT-induced pulmonary hypertension rats." (PMID 25420924, 2014). "Glycyrrhizin, an inhibitor of HMGB1, attenuates pulmonary hypertension progression and pulmonary vascular remodeling in the MCT-induced pulmonary hypertension rat model." (PMID 25420924, 2014). "Considering the cytokine activities of HMGB1, it is reasonable to propose that the effects of GLY on MCT-induced pulmonary hypertension shown in this work are related to the inflammatory processes of pulmonary hypertension." (PMID 25420924, 2014).
pulmonary hypertension (continued). "Based on our results linking HMGB1 and pulmonary hypertension, we tested the effects of GLY, an HMGB1 inhibitor, on hemodynamic features and vascular remodeling in MCT-induced pulmonary hypertension rats." (PMID 25420924, 2014). "This is in accordance with a previous study showing that sRAGE, but not HMGB1, was higher in patients with pulmonary hypertension, especially in PAH and chronic thromboembolic pulmonary hypertension." (PMID 37409127, 2023). "After inducing pulmonary hypertension through a single subcutaneous injection of MCT (60 mg/kg) to Sprague–Dawley rats, we administered daily intraperitoneal injections of either glycyrrhizin (GLY, 50 mg/kg), an inhibitor of HMGB1, or saline (control) for either 4 or 6 weeks." (PMID 25420924, 2014).
acute liver failure (29 papers, 2011 to 2025). Rapid deterioration of liver function causing encephalopathy and coagulopathy. "Lower patient numbers reached this secondary endpoint; however, the ability of HMGB1 to predict an increase in INR would be expected to translate into an ability to identify patients at risk of adverse outcomes such as acute liver failure and death." (PMID 29146439, 2018). "Emerging evidence shows that acute liver failure patients/animals have high concentrations of circulating HMGB1, which can contribute to multiple organ injuries and mediate gut bacterial translocation." (PMID 36855150, 2023). "The biocompatibility and HMGB1 adsorption performance of the HKT column were further studied in a d-galactosamine-induced acute liver failure swine model." (PMID 36855150, 2023). "We aimed to investigate the preventive effect of high mobility group box 1 (HMGB1)-A box and the mechanism by which it alleviates inflammatory injury in acute liver failure (ALF) by inhibiting the extracellular release of HMGB1." (PMID 36313316, 2022). "We then assessed the levels of the biomarker of ferroptosis including GPX4, FTH1, and HMGB1 using a public GEO dataset (GSE74000) obtained from patients with APAP-induced acute liver failure." (PMID 35198058, 2022). "Yet, GLY, a high mobility group protein B1 (HMGB1) inhibitor, has been shown to reduce the degree of ferroptosis of hepatocytes during acute liver failure (ALF) via activating NRF2/HO-1/HMGB1 pathway to antagonize oxidative stress." (PMID 35118067, 2021). "HMGB1 was also found to be a critical regulator of ferroptosis in many diseases, such as leukemia, acute liver failure, and diabetic nephropathy." (PMID 34336950, 2021). "High-mobility group box 1 (HMGB1) translocation participates in the development of acute liver failure." (PMID 33281190, 2020). "Additional evidence for an immune mediated acute liver failure stems from HMGB1 immunohistochemistry with its increased hepatocellular cytosolic expression (E3)." (PMID 27058902, 2016). "Another report has also suggested a limited role of HMGB1 in determining outcomes in acute liver failure (ALF) patients." (PMID 26383863, 2015). "High levels of HMGB1 have also been detected in the sera of patients with chronic hepatitis, acute liver failure and hepatitis B virus-related ACLF, demonstrating that HMGB1 release is associated with liver cell damage." (PMID 25187820, 2014). "In conclusion, cisplatin can protect against acute liver failure by retaining HMGB1 in the nucleus and preventing its release into the extracellular milieu." (PMID 23712360, 2013). "Because HMGB1 is a powerful inflammatory mediator in many diseases, the aim of this study is to evaluate the therapeutic effect of cisplatin acute liver failure." (PMID 23712360, 2013). "Researchers also found that miR-103a-3p agomiR was related to decreased septic liver injury with the suppression of inflammatory response and cell apoptosis targeting HMGB1 (high-mobility group B1), which is involved in the induction of inflammation and multiple organ failure in acute liver failure." (PMID 36012630, 2022). "Hmgb1 has been shown to be a promising therapeutic target for acute liver failure." (PMID 36291201, 2022). "Moreover, HMGB1 is also closely related to ferroptosis, and to be specific, inhibition of HMGB1 significantly reduces the degree of ferroptosis during acute liver failure." (PMID 34336950, 2021). "Increased levels of HMGB1 in serum and in HBV-infected hepatic tissue as well as the translocation of nuclear HMGB1 have been described in HBV-associated acute liver failure (ALF), and the serum levels of HMGB1 were positively correlated with disease severity in patients with CHB." (PMID 25892853, 2015). "To appreciate a potential role for HMGB1 in ALF, we investigated whether HMGB1 can be released by hepatocytes in the liver of patients or animals with acute liver failure/injury." (PMID 21406085, 2011).
acute liver failure (continued). "Likewise, HS could act as an anti-inflammatory agent that protected against acetaminophen (APAP)-induced acute liver failure by interacting with the high mobility group box 1 (HMGB1) protein." (PMID 41101498, 2025). "Moreover, GL effectively attenuated thyroiditis by inhibition of TLR2-HMGB1 signaling and reduced ferroptosis level during acute liver failure through the inhibition of oxidative stress pathways due to GL capacity on reducing HMGB1 and ROS (reactive oxygen species)." (PMID 34834206, 2021). "We found that the mRNA expressions of HMGB1, TLR4, and NF-κB were remarkably increased in acute liver failure model group." (PMID 23554835, 2013). "In drug-induced acute liver failure and ACLF models, there were significant decreases in serum HMGB1 levels and a reduction in liver injury after intervention with the anti-HMGB1 antibody, which ultimately contributed to the significantly improved animal survival." (PMID 36712653, 2022).
acute lung injury (29 papers, 2011 to 2026). A condition of lung damage that is characterized by bilateral pulmonary infiltrates (pulmonary edema) rich in neutrophils, and in the absence of clinical heart failure. "Some TLR4-activated danger-associated molecular pattern (DAMP) signals, including oxidized 1-palmitoyl-2-arachidonoyl-phosphatidylcholine (OxPAPC) and high-mobility group box 1 (HMGB1), are increased in the acute lung injury (ALI) caused by respiratory viruses such as the influenza virus." (PMID 34458281, 2021). "Blocking the HMGB1/TLRs/NF-κB pathway by lycorine to alleviate LPS-induced lung injury from inflammation and oxidative stress gave a new perspective for acute lung injury (ALI) therapy to be harnessed clinically." (PMID 37892993, 2023). "High-mobility group box1 (HMGB1), a key regulator of acute lung injury (ALI), is known to mediate the activation of the TLR4 (toll-like receptor 4)/NF-κB pathway; moreover, the block of this pathway has been shown to relieve LPS-induced acute lung injury." (PMID 37892993, 2023). "Dexmedetomidine (DEX) has been reported to attenuate cecal ligation perforation (CLP)-stimulated acute lung injury (ALI) by downregulating HMGB1 and RAGE." (PMID 34747306, 2021). "Previously, we have shown that high levels of airway high-mobility group box 1 protein (HMGB1) mediate hyperoxia-induced acute lung injury (HALI)." (PMID 32024151, 2020). "An investigation into the effects of SFI on the inhibition of the HMGB1-NF-κB pathway revealed the contribution of SFI to acute lung injury (ALI) in a rat model of endotoxin shock." (PMID 31781288, 2019). "PNU-282987, an α7nAChR-selective positive allosteric modulator, exerts protective effects against cardiopulmonary bypass-induced acute lung injury and inhibits high mobility group box-1 (HMGB1) release." (PMID 30134547, 2018). "There is accumulating evidence that generation of DAMPs such as oxidized phospholipids and high-mobility-group box 1 (HMGB1) during influenza virus infection leads to acute lung injury (ALI)." (PMID 29535197, 2018). "HMGB1 plays an important role in the initiation of innate immune responses to induce acute lung injury (ALI)." (PMID 25759027, 2015). "A recent study reported that SIRT1 is involved in the inhibitory action of (d-Ala2)-dynorphin 1-6 (leytragin), a peptide agonist of δ-opioid receptors, upon high mobility group box 1 (HMGB1) secretion in the lungs of mice with lipopolysaccharide (LPS)-induced acute lung injury." (PMID 36139497, 2022). "ARDS-associated acute lung injury (ALI) is characterized by widespread inflammation and subsequent alveolar epithelial-endothelial barrier damage, which are largely attributable to a variety of inflammatory mediators including TNF-α, IL-8, IFN-γ, and HMGB1." (PMID 33293898, 2020). "During acute lung injury (ALI), HMGB1 facilitates the polarization of macrophages toward the M1 phenotype and exacerbates ALI via the NF-κB signaling pathway mediated by TLR2 and TLR4." (PMID 41041277, 2025). "In the cecal ligation and puncture (CLP)-induced acute lung injury (ALI) model, inhibiting high mobility group box 1 (HMGB1) reduces caspase-11-dependent pyroptosis, thereby mitigating lung injury." (PMID 40832104, 2025). "In this animal approach, mice were treated with lipopolysaccharide (LPS) or recombinant high-mobility-group-protein B1 (HMGB1), which is a key mediator during inflammation to induce acute lung injury (ALI)." (PMID 32235291, 2020). "An increase in HMGB1 release has been observed during acute lung injury (ALI) under proinflammatory stimulation, but in the same model, autophagy stimulation was effective in reducing HMGB1 release and ALI." (PMID 32724296, 2020). "Likewise, HMGB1 is a relevant danger molecule and complement has been described to regulate HMGB1 release from human neutrophils such that, complement inhibition has proved to be protective in blast-induced acute lung injury in rats by ameliorating HMGB1-mediated inflammation." (PMID 30949180, 2019).
acute lung injury (continued). "However, prolonged exposure to hyperoxia results in acute lung injury (ALI) and accumulation of high mobility group box 1 (HMGB1) in the airways." (PMID 32600307, 2020). "High-tidal-volume mechanical ventilation and hyperoxia used in patients with acute lung injury (ALI) can induce the release of cytokines, including high-mobility group box-1 (HMGB1), oxygen radicals, neutrophil infiltration, and the disruption of epithelial and endothelial barriers." (PMID 21726460, 2011).